IL6 (interleukin 6)
Diseases named in the same sentence as IL6 in open-access papers (continued):
Sharing a sentence is not in itself a finding about the gene and the disease.
Insulin resistance (continued). "Macrophages participate in inflammatory pathways including JNK, IKK/NF-κB, and JAK/STAT through secreting inflammatory factors, such as TNF-α, IL-6, IL-1β, and LTB4, thereby inducing chronic inflammation of adipose tissue, liver, and muscle, further leading to insulin resistance." (PMID 36230963, 2022). "TNF-α was also reported to be elevated in skeletal muscle tissues, inducing the secretion of IL-6, IL-8, and monocyte chemotactic protein 1 (MCP-1), which may induce insulin resistance." (PMID 35408874, 2022). "Stevia also could lower the interleukin‐6 (IL‐6), IL‐1, and TNF‐α and thus could help in lowering insulin resistance in patients with diabetes." (PMID 36171777, 2022). "Moreover, punicic acid (5, 10, and 30 μM) significantly attenuated the levels of IL‐6, IL‐1β, and IFN‐γ following the TNF‐α‐induced insulin resistance in three T3‐L1 adipocyte cells." (PMID 36541264, 2022). "Moreover, TNF-α, IL-6, IL-1β, IFN-γ are also related to insulin resistance in the pediatric population." (PMID 36146688, 2022). "Visfatin, an adipokine present mainly in visceral adipose tissue, which induces the production of IL-6, IL-1β, and TNF-α, has a crucial inflammatory impact on the liver and maybe also related to insulin resistance." (PMID 35052633, 2022). "A proinflammatory diet might contribute to the risk of T2D by elevating circulating levels of inflammatory cytokines (e.g., interferon γ, IL-1, IL-6, IL-8, CRP, and TNF-α), which can lead to insulin resistance." (PMID 35685508, 2022). "Furthermore, IL-6 and TNF-α enhance the survival of inflammatory factors such as resistin, reinforcing insulin resistance." (PMID 36355818, 2022). "We observed thatthe mRNA expression levels of IL-1, MCP-1, and IL-6 were significantly reduced inadipose tissue of mice with P3HA4 silencing, which may be relatedto the improvement of insulin resistance induced by P3HA4silencing." (PMID 35976267, 2022). "They found apnoeic males showed higher hsCRP, IL-6, leptin, and insulin resistance than controls, while no significant influence can be observed in these biomarkers after CPAP treatment." (PMID 36105285, 2022). "Grape powder extract (rich in quercetin-3-glucoside, catechin, epicatechin, rutin, gallic acid and resveratrol) showed to decrease LPS-stimulated inflammation in macrophages by affecting the gene expression of IL-6, IL-8, IL-1β and TNF-α, and in turn decreased insulin resistance." (PMID 35057523, 2022). "Any abnormal change in pro-inflammatory cytokines (IL-6 and TNF-α) could diminish insulin sensitivity and contribute to insulin resistance." (PMID 36014565, 2022). "Studies have shown that the abundance of Subdoligranulum is positively correlated with microbial richness and HDL-cholesterol levels, and negatively correlated with fat mass, adipocyte diameter, insulin resistance, leptin, insulin, CRP, and IL6 levels in people and animals." (PMID 36611702, 2022). "Taken together, inflammation induced by pro-inflammatory cytokines such as IL-6 and TNF-α is inversely correlated with insulin signaling where it might lead to insulin resistance." (PMID 36504710, 2022). "Furthermore, in post-intervention, we observed trends between Il-6 and insulin resistance measured by HOMA-IR (r = 26, p = 0.07), and Il-6 and plasma insulin values at 120 min during OGTT (r = 0.24, p = 0.10)." (PMID 35323474, 2022). "Notable proinflammatory agents that directly affect signaling pathways related to insulin resistance, dyslipidemia, and/or vascular dysfunction/hypertension include tumor necrosis factor-α (TNF-α), interleukin-6 (IL-6), interleukin-1β (IL-1β), and monocyte chemoattractant protein-1 (MCP-1)." (PMID 35887592, 2022). "Not only increased PGRN levels in blood correlated positively with body mass index (BMI), fat mass, fasting glucose and insulin levels, and insulin resistance, but also mediated TNF-a-induced insulin resistance through the regulation of IL-6 expression in 3T3-L1 adipocytes." (PMID 35419363, 2022).
Insulin resistance (continued). "Furthermore, the treatment of T2DM mice with MEP resulted in reduced endotoxemia and insulin resistance-related pro-inflammatory cytokines interleukin 1β (IL-1β), tumor necrosis factor-alpha (TNF-α), and interleukin 6 (IL-6)." (PMID 36276816, 2022). "The results in addition showed insulin resistance, hyperinsulinemia, hyperandrogenism and oxidative stress as well as a significant increase in inflammatory biomarkers (NF-kB/TNF- and IL-6), with a significant decrease in TG, TC, FFA, GSH and G6PD in the adipose tissue of PCOS animals." (PMID 36071485, 2022). "Third, we had no available data on CRP, insulin resistance, and inflammatory parameters such as tumor necrosis factor and IL-6, since they were not routinely measured." (PMID 35572991, 2022). "Dietary supplementation of resveratrol during late pregnancy showed a positive effect on the placental function of sows, with ameliorated insulin resistance (HOMA-IR), increased triglyceride (TG) levels, and reduced levels of inflammatory cytokines, such as IL-1β and IL-6." (PMID 36407549, 2022). "Supporting the dependence of proinflammatory functions of ATMs on their glycolytic metabolism, HFD-fed mice with PDK2/4-deficient bone marrow display lower ATM numbers and inflammation (TNFα, IL-6 and CCL2 expression) in WAT as well as ameliorated insulin resistance." (PMID 34876704, 2022). "Kupffer cells play a major role in liver insulin resistance induced by HFD feeding through producing various inflammatory mediators, including TNF-α, IL-6, IL-1β, prostaglandins, and reactive oxygen species, which play vital roles in promoting the development of insulin resistance." (PMID 36230963, 2022). "Each of these models exhibits insulin resistance and impaired glucose metabolism, which was demonstrated by a glucose tolerance test (GTT) and insulin tolerance test (ITT), and systemic inflammation characterized by elevated plasma IL-6 and TNF-α levels." (PMID 35327570, 2022). "An increased production of TNF, IL-6, MCP-1, and other products of macrophages and other cells that occupy adipose tissue may consequently also play a role in the development of insulin resistance." (PMID 35959181, 2022). "IL-6 is a marker of the MetS, but TNF-alpha is involved in insulin resistance and dyslipidemia." (PMID 35053667, 2022). "TNF-α and IL-6 suppress insulin receptor substrates 1 (IRS-1) and 2 (IRS-2) and glucose transporter-4 (GLUT-4) while upregulating suppressor of cytokine signaling-3, resulting in insulin resistance." (PMID 35887592, 2022). "Spearman correlation analysis showed that GRB2 concentrations were negatively correlated with HDL-C, and positively associated with duration of diabetes, waist-to-hip ratio (WHR), TC, HBA1c, FPG, FINS, homeostasis model assessment-insulin resistance index (HOMA-IR), Hs-CRP, IL-6 and CIMT (P<0.01)." (PMID 36176460, 2022). "Although SC-fed IL-6Ra KD mice exhibit elevated plasma IL-6 levels, they do not display insulin resistance, as denoted by the insulin tolerance tests." (PMID 35470093, 2022). "Additional in vivo experiments revealed that asprosin augmented glucose intolerance, insulin resistance, endoplasmic reticulum (ER) stress, as well as circulation of pro-inflammatory cytokines (monocyte chemoattractant protein-1, MCP-1; IL-6; and TNFα) in mice." (PMID 36613673, 2022). "TNFα and IL-6, through classical receptor-mediated processes, stimulate both the JNK and the IκB kinase-β (IKK-β)/(NF-κB) pathways, leading to upregulation of inflammation mediators, and further to insulin resistance." (PMID 34068151, 2021). "In an Italian study, IL-6 was found to be significantly increased in all insulin-resistant PCOS, independent of BMI, but there was no increase in serum TNFα levels." (PMID 33997590, 2021). "These macrophages secrete TNF-α, IL-6, IL-1b and MCP1, which induce insulin resistance." (PMID 34683361, 2021).
Insulin resistance (continued). "Variables of body composition (BMI, waist to hip ratio) and insulin resistance were correlated with CRP or IL-6, while parameters of hyperandogenism were not." (PMID 33849511, 2021). "These include adiponectin, resistin, interleukin-6 (IL-6), tumor necrosis factor-α (TNF-α), and monocytic chemotactic protein (MCP-1) that influence not only body weight homeostasis but also insulin resistance, diabetes, lipid levels, inflammation, and atherosclerosis development." (PMID 33865458, 2021). "Thus, previous studies have suggested that insulin resistance resolution could be a factor driving the reduction in systemic inflammation by showing significant reductions in HOMA-IR before considerable reductions in the levels of IL-6, MCP-1, IL-18, TNF-α19,43,44." (PMID 34108550, 2021). "In addition, it has been shown that 10 nm GNPs control hyperglycemia in diabetic rats via regulating blood glucose levels, insulin resistance, pro-inflammatory mediators (CRP, IL-6 and TNF-α), and liver enzymes." (PMID 34572503, 2021). "Additionally, it can regulate the gut microbiota, increase IL-10, and reduce IL-6 and tumor necrosis factor-α (TNF-α), as well as liver injury, and further reduce insulin resistance and regulate lipid metabolism disorders." (PMID 34574191, 2021). "Overall, it may suggest that miRNA-126 would improve the insulin resistance through regulating NF-κB signaling and secretion of inflammatory biomarkers including TNF-α and IL-6." (PMID 34077450, 2021). "After 12 months of TRE, body mass was reduced by 3.4% and inflammatory markers (IL-6, IL-1β, and TNF-α), lipid profile (HDL, LDL, TG), and insulin resistance (fasting glucose, insulin, HOMA-IR) significantly improved compared with ND without affecting muscle performance." (PMID 34649266, 2021). "Bariatric surgery is associated with decreases in CRP and interleukin-6 concentrations in proportion to weight less, however, TNF-alpha levels did not change Despite this, insulin resistance was not normalized and some adipose pathology remained post-surgery." (PMID 34760952, 2021). "IL-6 seems to induce insulin resistance and an increased production of CRP in the liver and TNF-α may also induce insulin resistance by suppressing the expression of the insulin-sensitive glucose transporter in peripheral tissues." (PMID 34650454, 2021). "This drug induces inflammatory reactions in insulin resistance by inhibiting TNF-α and IL-6." (PMID 34037093, 2021). "On the other hand, increased IL-6 and TNF-α serum levels represent the insulin resistance state." (PMID 34572503, 2021). "IL-6 showed a significant positive correlation with insulin sensitivity and significant negative correlation with insulin resistance and serum glutamate pyruvate transaminase." (PMID 33997590, 2021). "An animal study comparing IL-6-/- mice with littermate control mice demonstrated that mice in the absence of IL-6 develop glucose intolerance and insulin resistance." (PMID 33997590, 2021). "The roles of IL-6, TNF- α, CRP, and IGF-1 in insulin resistance have been widely studied." (PMID 33432036, 2021). "Moreover, there are lots of mediators of insulin resistance that participate in driving renal function decline, including TGF-β1, blood pressure, inflammation, TNF-α, IL-6, and oxidative stress." (PMID 33628839, 2021). "Moreover, IL-6 and TNF-α, are involved in increased hepatic SREBP-1c expression and insulin resistance, via the increased expression of SOCS in the liver." (PMID 33584134, 2021). "The production of TNF-alpha, IL-6, and CRP from adipose tissue influences insulin resistance." (PMID 34403431, 2021). "TNF induced insulin resistance in adipocytes by inhibiting insulin-induced IRS1 tyrosine phosphorylation and insulin-induced glucose uptake and played a role in angiogenesis by inducing VEGF production synergistically with IL-1B and IL-6." (PMID 34306139, 2021).
Insulin resistance (continued). "Moreover, macrophage and Kupffer cell infiltration contribute to the progression of NAFLD and insulin resistance secreting pro-inflammatory cytokines such as TNF-α, IL-6 and IL-1β." (PMID 34684533, 2021). "With increase in EAT thickness, the levels of CRP, IL-6, visfatin, and JAZF1 also increase, which can induce hyperglycemia, insulin resistance, and vascular endothelial dysfunction, etc., promoting the occurrence and development of atherosclerosis, leading to macroangiopathy." (PMID 33722242, 2021). "Possible mechanisms of pathogenesis of NAFLD induced by H. pylori include (i) insulin resistance; (ii) inflammatory cytokines or adipokines, particularly CRP, TNF‐α, and IL‐6; (iii) altered lipid profile; and (iv) altered intestinal permeability and gut microbiota." (PMID 33490615, 2021). "Among the various inflammatory mediators, leptin, IL-6 and TNF-α are the major pro-inflammatory mediators that paly their decisive role to induce the inflammatory responses during the pathogenesis of DM and development of insulin resistance." (PMID 31929574, 2020). "IL-6 downregulates glucose transporter 4 expression and insulin receptor substrate-1 (IRS-1), resulting in reduced transport of glucose into cells (including myocytes) and aggravation of insulin resistance." (PMID 33222694, 2020). "Increases in IL-6 and TNF-α were also observed, particularly in the PCOS insulin resistance group." (PMID 32187268, 2020). "Not only IL6 and TNF-α increase but insulin resistance develops as well." (PMID 33643281, 2020). "CRP has been shown to play an active role in hepatic insulin resistance, at least partly through impairment in insulin signalling, independent of IL-6." (PMID 32828613, 2020). "The impact of H. pylori infection on other organs could be mediated by increased levels of inflammatory markers such as IL-6 and tumor necrosis factor-α (TNF-α), all of which are also involved in the development of insulin resistance and T2DM." (PMID 33013895, 2020). "It is well-known that the overproduction of proinflammatory cytokines TNFα, IL-1β, IL-6, and MCP-1 might play a critical role in the development of insulin resistance and chronic inflammation in obese animals." (PMID 33297496, 2020). "TNF-α and IL-6 can alter insulin sensitivity and stimulate the phosphorylation of serine residues instead of tyrosine in insulin receptor substrate-1 (IRS-1), thus inhibiting the activation of insulin signaling and sustaining insulin resistance." (PMID 32947869, 2020). "The M1 macrophage may promote the development of insulin resistance through secretion of proinflammatory cytokine such as TNF-α, IL-6, and IL-1b in response to stimulation by INF-γ." (PMID 32971975, 2020). "Moreover, elevated expression of IL‐6 was considered to be related to development of T2DM and insulin resistance." (PMID 32633001, 2020). "Blockade of IL-6 trans-signalling in adipose decreased macrophage recruitment, but did not alter insulin resistance, similar to our in vitro findings." (PMID 32603641, 2020). "Due to its broad tissue distribution, IL-6 is also involved in non-immune events including pathogeneses of insulin resistance, diabetes, and depression." (PMID 32655424, 2020). "Notably, IL6, NFKBIA, NFKB1, NOS3, PTPN1, PIK3R1, and STAT3 (members in the enriched WGCNA module) have been shown to alter insulin resistance." (PMID 33005175, 2020). "When excessive energy is ingested, WAT stores energy in the form of triglycerides in unilocular white adipocytes, and it secretes many adipokines such as tumor necrosis factor-α (TNF-α), interleukin-6 (IL-6), and plasminogen activator inhibitor-1 (PAI-1), which induce insulin resistance." (PMID 31346340, 2019). "Significant correlation of IL-6 with TNF-α and insulin resistance was observed that may provide us a therapeutic target for preventing metabolic derangements from insulin resistance." (PMID 30635365, 2019).
Insulin resistance (continued). "Inflammation and insulin resistance are closely related and inflammatory cytokines such as TNF-α, interleukin (IL)-6, IL-1, and IL-8 may inhibit insulin signaling via multiple mechanisms." (PMID 31331342, 2019). "Inflammation and insulin resistance are closely related, and inflammatory cytokines such as TNF-α, IL-6, IL-1, and IL-8 may inhibit insulin signaling via multiple mechanisms." (PMID 31118902, 2019). "IL-6 demonstrates the effect on glucose metabolism by altering the IRS,Glut-4, and insulin receptor,which support in boosting the rate of insulin resistance." (PMID 31524015, 2019). "In summary, our results show that high glucose administration results in glucose intolerance with insulin resistance through impairment of GLP-1 secretion, elevated level of blood glucose, activation of TLR4 and subsequently increased levels of IL-6 and TNF-α in mice." (PMID 31138952, 2019). "Injection of AD-MSCs reduced liver weight and steatosis by inhibiting pro-inflammatory genes including IL-6, TNF-α, and F4/80 expression (represented macrophage infiltration) and alleviating insulin resistance might via increasing IRS expression." (PMID 31455405, 2019). "In this study, we found that FGF-1 had positive effects on glucose intolerance, hepatic lipid accumulation, and insulin resistance, while it markedly repressed cytokine secretion (TNF-α and IL-6) in serum and reduced liver inflammation in diet-induced obesity (DIO) mice." (PMID 31866871, 2019). "Previous studies suggest that several cytokines and inflammatory mediators in the plasma are up-regulated in insulin resistance, including tumor necrosis factor-α (TNF-α), monocyte chemotactic protein-1 (MCP-1), C-reactive protein (CRP), and interleukin-6 (IL-6)." (PMID 31035653, 2019). "Elevation in release of pro-inflammatory cytokines such as IL-6 and TNF-α may induce a low-grade inflammatory state and oxidative stress, eventually leading to insulin resistance." (PMID 31569345, 2019). "Intriguingly, high-glucose load failed to impair glucose tolerance and did not change the levels of plasma IL-6 and TNF-α in TLR4 knockout mice, which suggests a critical role of TLR4 in increase of IL-6 and TNF-α levels and glucose intolerance and insulin resistance induced by high-glucose load." (PMID 31138952, 2019). "There are a large number of inflammatory mediators, such as C-reactive protein (CRP), interleukin-6 (IL-6), and plasminogen activator inhibitor-1 (PAI-1), that are elevated in the plasma of obese patients or animals and are closely related to insulin resistance." (PMID 31440472, 2019). "JQJT tablets could also reduce the levels of TNF-α, IL-6, and MCP-1, which were related to insulin resistance." (PMID 30733971, 2019). "One key mechanism of relaying inflammatory processes between fat, liver, and gut during NAFLD is the release of cytokines such as IL-1β, IL-6, IFN-γ, and TNF-α, which aggravate local inflammation, thereby worsening insulin resistance and triglyceride accumulation in fat and liver tissue." (PMID 30405618, 2018). "In addition, fat cells secrete signaling factors, for example, interlukein-6 (IL-6) and tumor necrosis factor-α (TNF-α) which are involved in the development of insulin resistance." (PMID 29853887, 2018). "The significant increase in the proinflamatory cytokines TNF-α, IL-6, RBP4, and progranulin, has contributed to promoting insulin resistance and triggering the inflammatory response, resulting in activation of HSCs to produce collagen and stimulate liver fibrosis." (PMID 30096951, 2018). "During diabetes, an increased level of TNF-α showed the effect on the insulin receptor and decreased the insulin sensitivity, while IL-6 shows the effect on the glucose via altering the insulin receptor, IRS, glut-4, which increase the incidence of insulin resistance." (PMID 35542112, 2018).